RNU6-831P (RNA, U6 small nuclear 831, pseudogene)
Gene: Small nuclear RNA gene on chromosome 18 (3,894,699 to 3,894,805, reverse strand). Ensembl gene ENSG00000207278.
Homologues: Orthologues: chimpanzee U6 (97% identical), macaque U6 (93% identical), mouse Gm23794 (82% identical). Paralogues in human: RNU6-1042P (91% identical), RNU6-698P (91% identical), RNU6-891P (91% identical), RNU6-1060P (90% identical), RNU6-116P (90% identical), RNU6-15P (90% identical), RNU6-378P (90% identical), RNU6-1145P (89% identical), RNU6-1303P (89% identical), RNU6-1316P (89% identical), RNU6-166P (89% identical), RNU6-25P (89% identical), and 1284 more.